CDKN1C (cyclin dependent kinase inhibitor 1C)
Diseases named in the same sentence as CDKN1C in open-access papers (continued):
Sharing a sentence is not in itself a finding about the gene and the disease.
colon carcinoma (8 papers, 2020 to 2026). "High expression of miR-221 enhances the invasion and metastasis of colon cancer cells (CRC) by targeting CDKN1C and RECK." (PMID 41602427, 2026). "Recently, STEAP3-AS1 was also reported to regulate cell cycle by modulating CDKN1C expression in colon cancer, but the detailed mechanisms were not fully understood." (PMID 35986274, 2022). "Previous studies have shown that the lncRNA STEAP3-AS1 affects the expression of CDKN1C, CDK2, and CDK4 and histone H3 acetylation, which are involved in regulating cell cycle progression in colon cancer." (PMID 40665344, 2025). "Studies of the transfection of colon carcinoma cells with a BMP5-expressing viral vector demonstrated that these cells overexpress a cell cycle regulator and tumor suppressor, cyclin-dependent kinase inhibitor 1C (CDKN1C), compared to cells in which BMP5 is down-expressed." (PMID 32722068, 2020).
Adrenal insufficiency (7 papers, 2017 to 2022). Insufficient production of steroid hormones (primarily cortisol) by the adrenal glands. "In all cases with functional CDKN1C variants, adrenal insufficiency should be excluded." (PMID 33076988, 2020). "Recently, a maternally inherited CDKN1C missense mutation (p.Arg279Leu) was identified in several members of a single family clinically diagnosed with Silver–Russell syndrome (SRS) but without adrenal insufficiency." (PMID 33076988, 2020). "Though no apparent adrenal insufficiency was observed in either the family in this study or those reported by Brioude or Kerns, we suggest that patients with RSS due to the CDKN1C PCNA domain‐related mutations should have a short synacthen test to rule it out." (PMID 31976094, 2019).
glioma (7 papers, 2009 to 2025). A benign or malignant brain and spinal cord tumor that arises from glial cells (astrocytes, oligodendrocytes, ependymal cells). "Ablation of endogenous miR‐25 restored expression of CDKN1C and significantly inhibited proliferation of glioma cells by promoting normal cell‐cycle progression." (PMID 32090490, 2020). "CDKN1C is regulated by p73 during mitotic exit and re-entry into G1 in T98G glioma cells and in myogenic differentiation, CDKN1C expression is induced by p73 and p63 to maintain pRB in an active hypophophorylated state." (PMID 19221586, 2009). "CDKN1C inhibition by miR-25 is also known to induce glioma cell proliferation and invasion." (PMID 32308561, 2020). "In glioma, miR-25 promotes glioma cells proliferation by targeting CDKN1C." (PMID 31316723, 2019).
neuroblastoma (7 papers, 2013 to 2025). Neuroblastoma (NB) is the most common solid, extracranial childhood tumor. "CDKN1C mutations are associated with tumor development in approximately 7% (neuroblastoma > nephroblastoma)." (PMID 35804856, 2022). "Further support for our model comes from genome-wide analyses showing that CDKN1C and ID2 are likely to be direct targets of ASCL1 in GBM and neuroblastoma cells." (PMID 35149717, 2022). "When MYCN was knocked-down by RNAi in selected neuroblastoma cell lines, cyclin A1 (CCNA1, OMIM 604036) and cyclin G2 (CCNG2, OMIM 603203) were upregulated alongside the cyclin-dependent kinase inhibitor CDKN1C, suggesting a functional connection between MYCN amplification and cell cycle control." (PMID 35804856, 2022).
Obesity (7 papers, 2018 to 2024). Accumulation of substantial excess body fat. "Further to this, we show that the loss of imprinting of Cdkn1c protects against diet-induced obesity." (PMID 30213134, 2018). "Increased expression of Cdkn1c is protective against diet-induced obesity in mice, and in humans increased caloric intake results in decreased CDKN1C expression." (PMID 35356864, 2022). "However, with obesity, we observed increased accessibility of genes involved in cell cycle regulation (ATM, CDKN1C, BCL2L11), autophagy (HSPA8, IRF8, PEX5), and protein catabolism (CDC34, CTSB, UBB)." (PMID 39872537, 2024). "Ultimately, drugs aimed at Cdkn1c may provide a way to increase BAT thermogenesis in adult humans to increase whole-body energy expenditure and address the global epidemic of obesity." (PMID 30213134, 2018). "Although their contribution to leptin expression has not been reported, Plagl1, Cdkn1c, and Kcnq1ot1 have been found to be involved in adiposity and obesity, implying that they may impact leptin expression in the adipose tissue." (PMID 36618698, 2022).
ovarian carcinoma (7 papers, 2012 to 2021). A malignant neoplasm originating from the surface ovarian epithelium. "Ovarian cancer cell line with acquired resistance to carboplatin revealed low levels of the gene cyclin-dependent kinase inhibitor 1C (CDKN1C), and demethylation agent can reverse the silencing of CDKN1C and increased the apoptotic response to carboplatin." (PMID 26900348, 2016). "Two genes (CTNNA1, CDKN1C) are common in breast and ovarian cancers." (PMID 31205821, 2019).
glioblastoma (6 papers, 2013 to 2024). The most malignant astrocytic tumor (WHO grade IV). "The miR-25 and CDKN1C (p57) axis seem to play a central role in the regulation of cell cycle re-entry not only in glioblastoma and cancerous cell proliferation but also in healthy conditions and after ischemia/reperfusion injury as mentioned in the previous section." (PMID 29765562, 2018). "MiRNA 221-3p binding to CDKN1C, demonstrated in glioblastoma and thyroid papillary carcinomas cells, respectively, may also play a role in cell cycle progression in the setting of myocyte proliferation in the setting of myocardial ischemia." (PMID 24432306, 2013). "Using a genetic approach in glioblastoma, miR-221/222 was demonstrated to downregulate the cell cycle inhibitors/tumor suppressors CDKN1B (p27 gene) and CDKN1C (p57 gene), resulting in enhanced cell proliferation." (PMID 37370750, 2023). "Interestingly, the knockdown of SMARCB1 in glioblastoma and medulloblastoma generated little effect on the LIN28B levels and the expression of CCND1 and CDKN1C." (PMID 27095948, 2016).
preeclampsia (6 papers, 2010 to 2024). Preeclampsia is a hypertensive disorder of pregnancy that is characterized by new-onset hypertension with proteinuria presenting after 20 weeks of gestation, and depending on mild or severe forms may initially present with severe headache, visual disturbances, and hyperreflexia. "Loss of function of CDKN1C may also play a role in preeclampsia/HELLP syndrome which has also been partially supported by animal studies." (PMID 26162698, 2015). "Interestingly, transgenic mice whose litters carry mutations of the maternal Cdkn1c copy display preeclampsia-like features, including hypertension, proteinuria, and abnormal trophoblast proliferation." (PMID 20617174, 2010). "The effect of each of these variables on IUGR was significant [Log10 CDKN1C expression, Exp (B) 4.91, 95% CI 1.09–22.10, p = 0.038; preeclampsia, Exp (B) 5.78, 95% CI 1.12–29.73, p = 0.05], indicating an independent effect of each of these factors on IUGR." (PMID 27200075, 2016). "The final statistical model (Nagelkerke R2 0.172, p = 0.002) included expression of CDKN1C and presence of preeclampsia." (PMID 27200075, 2016). "A comprehensive clinical evaluation, with genetic testing focused on screening for mutations in the CDKN1C gene, which is commonly associated with BWS, was conducted in a newborn diagnosed with BWS born to a mother with a history of preeclampsia and HELLP syndrome." (PMID 37686168, 2023). "Cyclin-dependent kinase inhibitor 1C (CDKN1C) (regulator of cell proliferation and cell cycle regulation), a maternal growth inhibitor gene, was dysregulated in preeclampsia and upregulated in the SGA placenta." (PMID 34833476, 2021). "In a recent study of 96 cases of BWS, seven resulted from maternally inherited CDKN1C mutations and of these, three pregnancies were complicated by preeclampsia, compared to three of the 89 BWS cases not related to CDKN1C mutations." (PMID 20617174, 2010).
adrenal hypoplasia (5 papers, 2017 to 2023). "The second group is adrenal hypoplasia, including X-linked adrenal hypoplasia congenita (AHC) caused by NR0B1, adrenal hypoplasia caused by steroidogenic factor-1/NR5A1, IMAGe syndrome caused by CDKN1C and MIRAGE syndrome caused by SAMD9." (PMID 34193132, 2021).
cervical carcinoma (5 papers, 2011 to 2024). A carcinoma arising from either the exocervical squamous epithelium or the endocervical glandular epithelium. "Using publicly available data of GC-growth-arrested cervical cancer cell line model (HeLa) that upregulate CDKN1C upon GC treatment, we observed binding of GR and multiple SWI/SNF members to the CERES enhancer, suggesting that this mechanism is active in other cancer types." (PMID 34272384, 2021).
liver cancer (5 papers, 2022 to 2024). An epithelial or non-epithelial malignant neoplasm that arises from the liver. "Recently, PIK3R3 was found to be upregulated in liver cancer; it activates Akt signaling to control cancer growth by regulating CDKN1C and SMC1A." (PMID 37644421, 2023). "Importantly, we verified that PIK3R3‐activated Akt signaling determined the expression of CDKN1C and SMC1A, two downstream of PIK3R3 in liver cancer cells." (PMID 37212524, 2023).
mole (5 papers, 2015 to 2025). "Absent or minimal expression of p57, a product of the maternally expressed CDKN1C gene, in the villi signifies a complete mole." (PMID 39057130, 2024).
growth disorders (4 papers, 2018 to 2024). "The 11p15.5 region containing CDKN1C is associated with growth disorders such as the Silver–Russell syndrome and the Beckwith–Wiedemann syndrome." (PMID 30310057, 2018).
leukemia (4 papers, 2009 to 2022). A malignant (clonal) hematologic disorder, involving hematopoietic stem cells and characterized by the presence of primitive or atypical myeloid or lymphoid cells in the bone marrow and the blood. "Analysis of the p57Kip2 methylation status in adult and childhood ALL found a rate of 50% CDKN1C hypermethylation in adult ALL but only 7% hypermethylation in childhood leukemia." (PMID 36033505, 2022). "Growth suppression in CDKN1C-transduced leukaemia cell lines is dependent on the extent of endogenous CDKN1C promoter methylation within the recipient cell background." (PMID 19221586, 2009). "Our BSP analysis demonstrated that the methylation levels of CDKN1C promoter are significantly higher in AML patients than that of the healthy controls, and MBD2 deficiency did not affect the methylation status of CDKN1C promoter regions in leukemia cells." (PMID 34789717, 2021). "In addition, our results were unable to observe significant association of the methylation of CDKN1C and RARA genes with leukemia." (PMID 24810788, 2014).
macrosomia (4 papers, 2019 to 2025). "In detail, BWS fetuses with IC1 GOM show extreme macrosomia and a severe disproportion between weight and length, while in IC2 LOM and CDKN1C mutated neonates, macrosomia is less pronounced and the weight/length ratio is more proportionate." (PMID 33810554, 2021). "Notably, miR-21 is one of several miRs that directly target CDKN1C, a further epigenetic mechanism linking dairy milk exosome intake during pregnancy to fetal macrosomia." (PMID 30602375, 2019).
prostate carcinoma (4 papers, 2013 to 2017). A carcinoma that arises from epithelial cells of the prostate gland. "Overexpression of PLAGL1 induced IGF2, H19, and CDKN1C expression in a prostate cancer cell line." (PMID 26115033, 2016).
Wilms tumor (4 papers, 2014 to 2021). An embryonal neoplasm characterized by the presence of epithelial, mesenchymal, and blastema components. "KCNQ1DN, which imprinted and mapped between CDKN1C and KCNQ1 on chromosome 11p15.5, is usually associated with Wilms' tumor." (PMID 33835050, 2021). "Early clinical work determined that maternal CDKN1C expression was absent in Wilms' tumors, suggesting that maternally inherited loss-of-function mutations in CDKN1C can cause some of the classic symptoms of BWS." (PMID 32424032, 2020).
acute lymphoblastic leukaemia (3 papers, 2007 to 2022). "Most tumours occur in the first 6 years of life, although in certain cases, tumours are diagnosed after this age, such as a 10-year-old patient with a loss-of-function CDKN1C variant who developed T-type acute lymphoblastic leukaemia." (PMID 35954470, 2022). "And some studies have found that CDKN1C is often methylated in acute lymphoblastic leukemia, and methylation is associated with poor prognosis." (PMID 32117949, 2020).
astrocytoma (3 papers, 2004 to 2011). "CDKN1C is also not expressed in human astrocytomas however re-expression leads to a G1 block associated with hypophosphorylation of pRB, consistent with a tumor suppressor role." (PMID 19221586, 2009).
autosomal dominant polycystic kidney disease (3 papers, 2020 to 2024). Autosomal dominant form of polycystic kidney disease. "Up-regulation of miR-199a-5p through suppressing CDKN1C might promote cell proliferation in autosomal dominant polycystic kidney disease tissues, which is a genetic disorder characterized by the growth of numerous cysts in the kidney often causes renal failure with many serious complications." (PMID 36386835, 2022).
embryonal tumors (3 papers, 2005 to 2021). "The risk for embryonal tumors in BWS results primarily from dysregulation at the telomeric domain of 11p15 (gain of methylation at ICR1 and UPD) rather than at the centromeric domain (loss of methylation at ICR2 and pathogenic variants in CDKN1C)." (PMID 34803919, 2021). "This could be due to the small sample (only three individuals showed expression from one parent) or to the different cell types used here (LCLs) and in previous studies (developing brain and embryonal tumors for CDKN1C)." (PMID 30204804, 2018).
insulinomas (3 papers, 2017 to 2022). "Comparison of gene-expression signatures of proliferating juvenile human and mouse beta-cells with insulinomas revealed EZH2 as a key regulator of juvenile beta-cell proliferation along with PcG-target CDKN1C (encodes cell-cycle inhibitor p57Kip2)." (PMID 35602600, 2022). "The consistent reduction of CDKN1C relative to normal beta cells was confirmed both by DEG analysis as well as immunohistochemistry on a human insulinoma tissue microarray, and supports the putative imprinting abnormalities and CNV loss in the CDKN1C imprinted region on chromosome 11p15.5." (PMID 28974674, 2017).
microcephaly (3 papers, 2020 to 2025). A congenital or acquired developmental disorder in which the circumference of the head is smaller than normal for the person's age and sex. "In addition, loss-of-function mutations in CDKN1C can cause microcephaly." (PMID 38731817, 2024). "We found that the microcephaly phenotype was already evident from E13 onwards in Cdkn1c-MADM-7 with maternal and paternal deletion, respectively, and in cKO-Cdkn1c-MADM-7." (PMID 31924768, 2020). "Consequently, the cKO-Cdkn1c-MADM-7 mice exhibit very strong microcephaly, similar to Cdkn1c-MADM-7 mice with maternal deletion, and slightly more severe than with paternal deletion." (PMID 31924768, 2020). "Given that mosaic Cdkn1c-MADM-7 mice (all cells are Cdkn1cflox/+) with heterozygous Cdkn1c deletion in Emx1+ lineage show microcephaly similar like cKO-Cdkn1c-MADM-7 mice, we conclude that the growth-promoting function of Cdkn1c is also highly dosage sensitive." (PMID 31924768, 2020).
non-small cell lung carcinoma (3 papers, 2013 to 2017). A group of at least three distinct histological types of lung cancer, including non-small cell squamous cell carcinoma, adenocarcinoma, and large cell carcinoma. "CDKN1C (p57) is a direct target of EZH2 and is suppressed by epigenetic mechanisms in breast cancer, ovarian cancer, non-small-cell lung cancer etc.." (PMID 29371934, 2017).
papillary thyroid carcinoma (3 papers, 2013 to 2025). "Specifically, noteworthy are our findings regarding the potential diagnostic value of CCNA1 and SFN genes in papillary thyroid carcinoma, while the reduced expression of CDKN1C, FOS, and JUN genes in follicular carcinoma suggests their value in distinguishing the thyroid pathologies." (PMID 40722651, 2025).
alopecia (2 papers, 2017 to 2024). Hair loss usually from the scalp. "TAp63 keeps SKPs in quiescence through transactivation of Cdkn1c (also known as p57KIP2), thus preventing premature depletion of these cells, early aging of the skin, alopecia, and wound healing defects." (PMID 38165157, 2024).
Anxiety (2 papers, 2020 to 2024). Intense feelings of nervousness, tension, or panic often arise in response to interpersonal stresses. "To gauge the behavioural impacts of in utero LPD exposure and paternal Cdkn1c mis-expression, we subjected juvenile (4–5 week old) and adult (9–10 week old) offspring to an array of tasks designed to evaluate basic motor functions, as well as anxiety-related and cognitive functions." (PMID 38609446, 2024).
childhood cancer (2 papers, 2020 to 2022). "Intriguingly, loss‐of‐function of CDKN1C is a hallmark of human overgrowth syndromes including Beckwith‐Wiedemann and Costello, who are themselves at a higher risk of developing childhood cancer including FN‐RMS." (PMID 36037042, 2022). "Future investigations will interrogate the molecular nature of YAP1 and HES1 convergence on CDKN1C, the transcriptional program governed by HES1 in FN‐RMS tumorigenesis, and the impact on FN‐RMS cell fate decisions, informing potential therapeutic opportunities for this childhood cancer." (PMID 36037042, 2022).
chondrosarcoma (2 papers, 2020 to 2022). A malignant cartilaginous matrix-producing mesenchymal neoplasm arising from the bone and soft tissue. "Other in vitro studies recently showed, that tumor progression involved SOX9 and CDKN1C repression in different chondrosarcoma cell lines." (PMID 33076370, 2020).
cyst (2 papers, 2021 to 2022). A sac-like closed membranous structure that may be empty or contain fluid or amorphous material. "Inhibition of miR-199a-5p decreased cell proliferation and increased apoptosis of cyst epithelial cells through targeting CDKN1C/p57." (PMID 33809516, 2021). "While CDKN1B and CDKN1C expression was higher in normal subtypes, senescence-related CDK inhibitors CDKN1A and CDKN2A were more abundant in PKD-CDC subtypes, suggesting that cyst-lining cells may be prone to cellular senescence due to cellular stress." (PMID 36310237, 2022).
diffuse large B-cell lymphoma (2 papers, 2011 to 2022). "Hypermethylation of the CDKN1C gene, encoding for p57Kip2, occurs in diffuse large B-cell lymphoma (DLBCL), follicular lymphoma, ALL and nodal DLBCL." (PMID 36033505, 2022).
endometriosis (2 papers, 2013 to 2021). The growth of functional endometrial tissue in anatomic sites outside the uterine body. "Epigenetic alterations of a few genes (DLX5, CDKN1C, PTGER2, and GATA3) are common for endometriosis and obstetric complications." (PMID 34833476, 2021).
Ewing sarcoma (2 papers, 2013 to 2018). A small round cell tumor that lacks morphologic, immunohistochemical, and electron microscopic evidence of neuroectodermal differentiation. "CDKN1C and a related member of the FOXO family, FOXO1, have previously been shown to inhibit Ewing Sarcoma growth, while FOXM1, GLI1 and PDGFRB have been shown to be growth-promoting in Ewing Sarcoma." (PMID 30237855, 2018).